ERRFI1 (ERBB receptor feedback inhibitor 1)
Description:
Negative regulator of EGFR signaling in skin morphogenesis. Acts as a negative regulator for several EGFR family members, including ERBB2, ERBB3 and ERBB4. Inhibits EGFR catalytic activity by interfering with its dimerization. Inhibits autophosphorylation of EGFR, ERBB2 and ERBB4. Important for normal keratinocyte proliferation and differentiation. Plays a role in modulating the response to steroid hormones in the uterus. Required for normal response to progesterone in the uterus and for fertility. Mediates epithelial estrogen responses in the uterus by regulating ESR1 levels and activation. Important for regulation of endometrium cell proliferation. Important for normal prenatal and perinatal lung development (By similarity).
Synonyms: MIG-6; MIG6; GENE-33; RALT
Tractability: Antibody: UniProt places it where antibodies can reach, with medium confidence; its Gene Ontology location is reachable by antibodies, with medium confidence. PROTAC: ubiquitination databases record sites on it.
Gene: Protein-coding gene on chromosome 1 (8,004,404 to 8,026,312, reverse strand). Ensembl gene ENSG00000116285.
Subcellular location: Cytoplasm; Cell membrane; Nucleus
Subcellular location (Human Protein Atlas): Cytosol
Gene Ontology:
Molecular function: protein binding; protein kinase binding; GTPase activator activity; kinase binding; SH3 domain binding; small GTPase binding
Biological process: negative regulation of epidermal growth factor-activated receptor activity; negative regulation of protein autophosphorylation; lung alveolus development; lung epithelium development; lung vasculature development; negative regulation of epidermal growth factor receptor signaling pathway; regulation of keratinocyte differentiation; skin morphogenesis; cellular hyperosmotic response; cellular response to dexamethasone stimulus; cellular response to epidermal growth factor stimulus; cellular response to insulin stimulus; cellular response to platelet-derived growth factor stimulus; negative regulation of cardiac muscle hypertrophy in response to stress; negative regulation of collagen biosynthetic process; negative regulation of ERK1 and ERK2 cascade; negative regulation of interleukin-1 beta production; negative regulation of tumor necrosis factor production; regulation of type B pancreatic cell proliferation
Cellular component: cytosol; cytoplasm; plasma membrane; nucleus
Genetic constraint (gnomAD): Loss-of-function variants: 13 observed, 19 expected, observed/expected ratio (o/e) 0.68, 90% interval 0.44 to 1.09. The upper end of that interval is the gene's LOEUF score, 1.09, which puts it in group 4 of 6, group 1 being the genes least tolerant of losing a copy. Missense variants: 482 observed, 601.28 expected, observed/expected ratio (o/e) 0.8, 90% interval 0.74 to 0.86. Synonymous variants: 202 observed, 221.47 expected, observed/expected ratio (o/e) 0.91, 90% interval 0.81 to 1.02.
Homologues: Orthologues: chimpanzee ERRFI1 (99% identical), macaque ERRFI1 (98% identical), dog ERRFI1 (84% identical), rabbit ERRFI1 (84% identical), rat Errfi1 (82% identical), mouse Errfi1 (82% identical), guinea pig ERRFI1 (80% identical), pig ERRFI1 (75% identical), tropical clawed frog errfi1 (54% identical), zebrafish errfi1a (45% identical).
Diseases named in the same sentence as ERRFI1 in open-access papers:
ERRFI1 is named in the same sentence as 71 diseases in open-access papers, as found by Europe PMC text mining. Sharing a sentence is not in itself a finding about the gene and the disease. The quoted sentences say what the papers report.
breast carcinoma (13 papers, 2014 to 2025). "We found low expression of ERRFI1 in WT cancer tissues after comparing its expression in WT, and it has been reported that ERRFI1 is also frequently mutated or downregulated in breast cancer, lung cancer, and glioblastoma." (PMID 35480093, 2022). "Additionally, reduced ERRFI1 expression is associated with poor prognosis in breast cancer patients." (PMID 35859293, 2022). "Among them, OSMI‐1, a newly discovered small molecule OGT inhibitor, activates the tumour suppressor ERRFI1 through epigenetic mechanisms, thereby inhibiting breast cancer growth." (PMID 39358921, 2024). "Chemotherapy-resistant breast cancer cell lines treated with the OSMI-1 exhibited anti-tumor activity through epigenetic activation of the tumor suppressor ERRFI1." (PMID 37268905, 2023). "Studies indicate that ERRFI1 is downregulated in lung cancer, breast cancer, thyroid cancer, and many other cancer types." (PMID 34608122, 2021). "ERRFI1 is reported to induce apoptosis and inhibit proliferation and invasion in endometrial cancer, breast cancer, and thyroid cancer, suggesting ERRFI1 functions as a tumor suppressor in certain cancers." (PMID 34608122, 2021). "We show that ERRFI1 is selectively downregulated in ERα-positive breast cancers and breast cancers driven by ERBB2." (PMID 33046784, 2020). "In breast cancer, down-regulation of ERRFI1 expression is correlated with poor survival." (PMID 33869036, 2021). "ERRFI1 deletions have been found in glioblastoma multiforme and breast cancer." (PMID 24550739, 2014). "ERRFI1 is a negative regulator of the growth factor EGFR and has been identified in breast carcinoma as a gene altered by hypoxia." (PMID 37671061, 2023). "Our findings suggest a link between OGT and ERRFI1 signaling, pointing to OGT as a possible therapeutic target in a significant subset of breast cancer patients." (PMID 33046784, 2020). "The hypermethylation of ERBB receptor feedback inhibitor 1 (ERRFI1), paired-like homeodomain transcription factor 2 (PITX2) and downstream of kinase 7 (DOK7) promoters avoid PI3K/AKT/mTOR pathway inhibition conferring chemotherapy resistance to breast cancer." (PMID 39941901, 2025). "Consequently, it will be of great interest to determine how expression of Errfi1, and also its tyrosine phosphorylation, relate to HER2 expression and outcome in breast cancer patients." (PMID 25200860, 2014). "However, in breast cancer cells with low expression of ERRFI1, inhibiting DNA methyltransferase did not have any impact on the expression of this gene." (PMID 39143382, 2024).
glioblastoma (12 papers, 2010 to 2025). The most malignant astrocytic tumor (WHO grade IV). "ERRFI1 has been implicated in regulating cellular processes, such as apoptosis, migration, and invasion, demonstrating a tumor‐suppressive role in glioblastoma, liver cancer, and endometrial cancer cells." (PMID 39096122, 2024). "ERRFI1 has been found to be significant tumor suppressor gene and is frequently deleted, mutated or downregulated in various types of cancer, including glioblastomas." (PMID 36231068, 2022). "Our biological data are consistent with these previous findings, showing that restoring ERRFI1 expression in an ERRFI1-deficient glioblastoma cell line decreases glioblastoma cell migration." (PMID 21113414, 2010). "ERRFI1 is also frequently deleted, mutated, or down-regulated in breast and lung cancers, as well as in glioblastomas." (PMID 21113414, 2010). "We further investigated the possible pathogenic function of ERRFI1 in glioblastoma cells." (PMID 21113414, 2010). "Ectopic expression of Gene 33 in the H423 glioblastoma cell line with homozygous deletion of ERRFI1 suppresses cell migration." (PMID 34206547, 2021). "As in lung cancer, chromosome 1p36, where ERRFI1 is located, is among the genetic loci that are frequently deleted in glioblastoma." (PMID 34206547, 2021). "Remarkably, ERRFI1 is lauded as a tumor suppressor gene of glioblastomas, whose high expression can diminish the migration of glioblastoma cells." (PMID 33117083, 2020). "ERRFI1 has also been highlighted to function as a tumor suppressor in glioblastoma by eliminating the malignant potential of glioblastoma cells." (PMID 33117083, 2020). "MIG6 inactivation can be the result of loss of heterozygosity or focal deletion of ERRFI1, as reported in EGFR-amplified glioblastoma, or promoter methylation, as found in papillary thyroid carcinoma." (PMID 26788993, 2016). "We found that ERRFI1 is a potential glioblastoma-targeted tumor suppressor gene and TACC3 is a potential oncogene." (PMID 21113414, 2010). "We measured ERRFI1 mRNA levels in a panel of 62 glioblastoma samples and detected downregulation of ERRFI1 expression in 34% of the samples tested." (PMID 21113414, 2010). "Our genetic and biological data, as well as data from other studies, suggests that ERRFI1 is another key component in the EGFR signaling pathway involved in glioblastoma development." (PMID 21113414, 2010). "Our multifaceted genomic evaluation of glioblastoma establishes ERRFI1 as a potential candidate tumor suppressor gene and TACC3 as a potential oncogene, and provides insight on targets for oncogenic pathway-based therapy." (PMID 21113414, 2010). "In glioblastoma cells with a focal deletion of the ERRFI1 locus, restoration of ERRFI1 expression slowed cell migration." (PMID 21113414, 2010). "Moreover, ERRFI1 can be targeted for degradation by miRNA, such as miRNA-148 and miRNA-200, which have been shown to target ERRFI1 in glioblastomas and bladder cancer, respectively." (PMID 32432675, 2020). "We further demonstrated that ERRFI1 and TACC3 in 1p36.23 and 4p16.3, respectively, are potential glioblastoma-targeted genes." (PMID 21113414, 2010). "Paradoxically, all FGFR-fused glioblastomas shared strong PI3K and MAPK pathway suppression effected by SPRY, DUSP and AKAP12 inhibitors, whereas the FGFR2-TACC2 tumor elicited also EGFR suppression by ERRFI1 upregulation." (PMID 33853673, 2021). "In a recent study, overexpression of ERRFI1 was shown to decrease proliferation in glioblastoma cells, binding EGFR with STX8, and driving internalized EGFR to late endosomes for degradation, whereas knockdown of ERRFI1 expression resulted in increased tumor invasion." (PMID 21113414, 2010). "Glioblastoma cell line H423 harbors a homozygous deletion of ERRFI1 and did not express endogenous ERRFI1." (PMID 21113414, 2010).
lung carcinoma (11 papers, 2010 to 2025). "Previous studies showed that Errfi1 is selectively downregulated in cancer tissues, including breast, thyroid, and lung cancers, and its expression is associated with better prognosis, suggesting Errfi1 as a tumor suppressor gene." (PMID 39017946, 2024). "Based on Kaplan–Meier Plotter, we found that the expression level of ERRFI1 is associated with a positive prognosis in lung cancer patients." (PMID 33869036, 2021). "Loss of ERRFI1 not only promotes lung cancer cell proliferation and migration through the ERK pathway in vitro, but also causes spontaneous lung tumorigenesis in mice." (PMID 34608122, 2021). "Genetic analyses revealed polymorphisms and missense mutations of the ERRFI1 gene in some human lung cancer cell lines and primary lung cancer cells." (PMID 34206547, 2021). "Furthermore, the high expression level of ERRFI1 was associated with high overall survival rates in lung cancer patients." (PMID 33869036, 2021). "In a lung cancer model, the combination of ERRFI1 knockdown (shERRFI1) and anti-PD1 (α-PD1) therapy significantly reduced tumor burden (p < 0.0001) and improved survival rates, demonstrating a synergistic effect compared to monotherapy or the control group." (PMID 40308576, 2025). "Research has indicated that ERRFI1 is significant in the development of lung cancer, endometrial cancer, and breast cancer." (PMID 39239554, 2024). "Colony formation assays were performed to determine the effect of LC-C and the target gene ErbB receptor feedback inhibitor 1 (ERRFI1) on radiosensitivity of IR-resistant lung cancer cells." (PMID 33869036, 2021). "Tumor xenograft experiments were conducted to observe the effect of LC-C and ERRFI1 on radiosensitivity of IR-resistant lung cancer cells in vivo." (PMID 33869036, 2021). "In humans, deletion of the 1p36 locus of the chromosome, where ERRFI1 is located, occurs in nearly 50% of human lung cancer." (PMID 34206547, 2021). "Other potential oncogenic changes of ERRFI1 in human lung cancer patients, although at even lower frequencies, include frameshift insertions at serine 372 and threonine 187, and the fusion with DNAH2 (the TCGA database)." (PMID 34206547, 2021). "LC-C significantly enhanced the effect of radiation in IR-resistant lung cancer cells both in vitro and in vivo and validated ERRFI1 as a candidate downstream gene by RNA-seq." (PMID 33869036, 2021). "Further investigations are warranted to determine the regulation mechanism of LC-C on ERRFI1, which might contribute to develop more drugs for enhancing radiosensitivity of lung cancer." (PMID 33869036, 2021). "Forced expression of ERRFI1 alone could significantly increase the radiosensitivity of IR-resistant lung cancer cells, while silencing of ERRFI1 attenuated the radiosensitizing function of LC-C." (PMID 33869036, 2021). "Herein, our study demonstrated that LC-C could sensitize ionizing radiation-resistant lung cancer cells to IR treatment in vitro and in vivo, and the radiosensitization effects of LC-C correlated to the level of ERRFI1 expression." (PMID 33869036, 2021). "The current study demonstrated the LC-C sensitized ionizing radiation-resistant lung cancer cells to radiation both in vitro and in vivo, and the radiosensitization effect was attributed to the up-regulation of ERRFI1 and the down-regulation of EGFR/STAT3 pathway." (PMID 33869036, 2021). "Furthermore, the clinical significance of ERRFI1 in lung cancer patients was evaluated with Kaplan–Meier Plotter." (PMID 33869036, 2021). "ERRFI1 has been shown to promote apoptosis in lung cancer cells via the ERK pathway." (PMID 34608122, 2021). "Consequently, loss of ERRFI1 expression in human lung cancer cells showed no response to the activated EGF pathway." (PMID 33869036, 2021). "Our in vivo experiments demonstrated that knockdown of ERRFI1, a critical gene within the STING signature, significantly enhances antitumor immunity and synergizes with anti-PD1 therapy in a lung cancer model." (PMID 40308576, 2025).
lung carcinoma (continued). "The observed synergy between ERRFI1 inhibition and anti-PD1 therapy suggests a promising strategy for improving immunotherapy outcomes in lung cancer patients." (PMID 40308576, 2025). "Additionally, our in vivo experiments confirmed that knockdown of ERRFI1, a key gene within the STING signature (STINGsig), significantly enhances antitumor immunity and synergizes with α-PD1 therapy in a lung cancer model." (PMID 40308576, 2025). "Through in vivo experiments, we confirmed that knockdown of ERRFI1, a critical gene within the STINGsig, significantly enhances antitumor immunity and synergizes with α-PD1 therapy in a lung cancer model, underscoring its therapeutic potential in modulating immune responses." (PMID 40308576, 2025). "In addition, we found that ERRFI1-overexpression significantly enhanced radiation-induced G2/M arrest and also increased p21, p-CDC2 expression, reduced p-CHK2 expression in lung cancer cells." (PMID 33869036, 2021). "However, no ERRFI1 promoter methylation or histone acetylation were detected in selected lung cancer and melanoma cell lines." (PMID 34206547, 2021). "Interestingly, we observed that the miR‐205/ERRFI1/EGFR regulatory axis can operate also in not‐addicted cells, as ectopic miR‐205 expression in A549 lung cancer cells resulted in ERRFI1 downregulation and increased EGFR expression/activation." (PMID 30021798, 2018). "Interestingly, stable ectopic expression of the wild-type EGFR increases the ERRFI1 mRNA level but not the protein level whereas ectopic expression of the L858R mutant EGFR, which is a common EGFR mutant in lung cancer, elevates both the mRNA and protein levels of Gene 33 in H1299 lung cancer cells." (PMID 34206547, 2021).
glioma (7 papers, 2020 to 2025). A benign or malignant brain and spinal cord tumor that arises from glial cells (astrocytes, oligodendrocytes, ependymal cells). "Moreover, the genomic analysis of human gliomas revealed frequent focal deletions of ERRFI1, suggesting that the loss of MIG6 activity may contribute to the development of GBM through aberrant activation of EGFR." (PMID 39129344, 2025). "In addition, ERRFI1 was reported to have common focal deletions in analysis of 1,057 glioma cases while it could encode Mig6, a feedback inhibitor to block the activation of EGFR." (PMID 33117083, 2020). "Taken together, glioma-derived exosomal miR-148a-3p promoted tumor angiogenesis through activation of the EGFR/MAPK signaling pathway by ERRFI1 inhibition." (PMID 33117083, 2020). "We also observed that glioma tissues, cells and exosomes presented with down-regulated levels of the ERRFI1 gene." (PMID 33117083, 2020). "In the co-culture system, our data demonstrated that glioma cells-derived exosomal miR-148a-3p down-regulated ERRFI1 and activated the EGFR/MAPK signaling pathway, so as to promote cell proliferation and angiogenesis." (PMID 33117083, 2020). "Thus, the STAT3-dependent (as well as SOX2- and TCF3-dependent) increase in ERRFI1 expression provides the common glioma path for the regulation of EGFR signaling." (PMID 36231068, 2022). "Besides, glioma-derived exosomal miR-148a-3p reinforced angiogenesis through activating the EGFR/MAPK signaling pathway with the ERBB receptor feedback inhibitor 1 (ERRFI1)." (PMID 35095909, 2021). "Collectively, our obtained findings revealed that that miR-148a-3p delivered by glioma cells-derived exosomes could promote tumor angiogenesis by activating the EGFR/MAPK signaling pathway through inhibition of the ERRFI1 expression." (PMID 33117083, 2020). "Taken together, findings obtained in the current study demonstrate that glioma cells-derived exosomal miR-148a-3p activate the EGFR/MAPK signaling pathway by repressing the expression of the ERRFI1 gene, leading to the promotion of tumor angiogenesis in glioma." (PMID 33117083, 2020). "miR-148a-3p was highly expressed, while ERRFI1 was poorly expressed in glioma." (PMID 33117083, 2020). "Studies have further indicated that ERRFI1 may be closely related with glioma." (PMID 33117083, 2020). "In general, the activation of SPRY4, ERRFI1, and RAB31 can be used for developing new approaches to glioma therapy." (PMID 36231068, 2022). "We also detected that the upregulation of SPRY4, ERRFI1 and RAB31 provides a condition for feedback regulations of FGF and EGF signaling as well as can be applied in glioma therapy." (PMID 36231068, 2022). "In summary, our results demonstrated that up-regulation of miR-148a-3p by U251 cells-derived exosomes inhibited the ERRFI1 expression, so as to activate the EGFR/MAPK signaling pathway, thereby promoting glioma cell growth and angiogenesis in vivo." (PMID 33117083, 2020). "Interestingly, we found three commonalities for all analyzed glioma feedback regulators of the EGFR and FGFR signaling pathways: SPRY4, ERRFI1 and RAB31." (PMID 36231068, 2022). "Furthermore, we found three EGFR and FGFR signaling feedback regulators common to all analyzed gliomas—SPRY4, ERRFI1, and RAB31—which can be used for creating new therapeutic strategies of suppressing the invasion and progression of gliomas." (PMID 36231068, 2022). "The identification of the SPRY4, ERRFI1, and RAB31 as genes whose natural activation provides the inverse regulation of the processes of neurosphere formation can be used for creating new strategies of suppressing the invasion and progression of gliomas." (PMID 36231068, 2022).
endometrial cancer (5 papers, 2021 to 2024). Primary or metastatic malignant neoplasm involving the endometrium (mucous membrane that lines the endometrial cavity). "These are ERRFI1, IL6, PIK3R1 and SPRY2 which were found to be upregulated and YWHAZ which was found to be downregulated; Endometrial cancer has twelve genes." (PMID 34764329, 2021).